ADNP2 (ADNP homeobox 2)
Description:
May be involved in transcriptional regulation. May play a role in neuronal function; perhaps involved in protection of brain tissues from oxidative stress. May be involved in erythroid differentiation (By similarity).
Synonyms: KIAA0863; ZNF508
Tractability: PROTAC: UniProt records ubiquitination sites on it; ubiquitination databases record sites on it; its protein half-life has been measured.
Gene: Protein-coding gene on chromosome 18 (80,109,262 to 80,147,523, forward strand). Ensembl gene ENSG00000101544.
Subcellular location: Nucleus
Subcellular location (Human Protein Atlas): Cytosol; Mitochondria
Pathways (Reactome):
Chromatin organization: ChAHP complex assembly
Gene Ontology:
Molecular function: protein binding; DNA-binding transcription factor activity, RNA polymerase II-specific; DNA binding
Biological process: nervous system development; regulation of gene expression; regulation of transcription by RNA polymerase II
Cellular component: chromatin; nucleus
Genetic constraint (gnomAD): Loss-of-function variants: 6 observed, 13.22 expected, observed/expected ratio (o/e) 0.45, 90% interval 0.25 to 0.9. The upper end of that interval is the gene's LOEUF score, 0.9, which puts it in group 3 of 6, group 1 being the genes least tolerant of losing a copy. Missense variants: 1,378 observed, 1,448.9 expected, observed/expected ratio (o/e) 0.95, 90% interval 0.91 to 0.99. Synonymous variants: 633 observed, 566.44 expected, observed/expected ratio (o/e) 1.12, 90% interval 1.05 to 1.19.
Homologues: Orthologues: chimpanzee ADNP2 (99% identical), macaque ADNP2 (98% identical), pig ADNP2 (88% identical), dog ADNP2 (86% identical), rabbit ADNP2 (84% identical), guinea pig ADNP2 (83% identical), mouse Adnp2 (80% identical), rat Adnp2 (80% identical), rat Adnp2l1 (58% identical), tropical clawed frog adnp2 (41% identical), zebrafish adnp2b (28% identical), zebrafish adnp2a (26% identical). Paralogues in human: ADNP (23% identical).
Diseases named in the same sentence as ADNP2 in open-access papers:
ADNP2 is named in the same sentence as 12 diseases in open-access papers, as found by Europe PMC text mining. Sharing a sentence is not in itself a finding about the gene and the disease. The quoted sentences say what the papers report.
schizophrenia (5 papers, 2019 to 2024). A major psychotic disorder characterized by abnormalities in the perception or expression of reality. "Human mutations of ADNP and ADNP2 are known to be associated with neural developmental disorders (NDDs), including autism spectrum disorders (ASDs) and schizophrenia (SZ)." (PMID 39273418, 2024). "ADNP/ADNP2 control of erythropoiesis and ADNP/ADNP2 coregulation with dysregulation association with aging, as well as brain disorders, such as schizophrenia and Alzheimer’s disease." (PMID 39251453, 2024). "The ADNP paralogue ADNP2 has not (yet) been linked to any disorder, although some ADNP2 variants were named associated with the onset of schizophrenia." (PMID 36945042, 2023). "Interestingly, sexual differences were found in ADNP, ADNP2 expression in Alzheimer’s disease (lymphocytes) and in schizophrenia (postmortem brains and lymphocytes)." (PMID 32937737, 2020). "We argued that “increased ADNP and ADNP2 expression in lymphocytes from schizophrenia patients compared to healthy controls and a negative correlation with disease duration may be a compensatory mechanism." (PMID 31191249, 2019).
post-traumatic stress disorder (2 papers, 2024). An anxiety disorder precipitated by an experience of intense fear or horror while exposed to a traumatic (especially life-threatening) event. "ADNP is notably associated with ASD and developmental delay (DD), while the ADNP2 gene is closely linked with SZ, post-traumatic stress disorder (PTSD), ASD, and DD." (PMID 39273418, 2024). "Additionally, a de novo single nucleotide variation in ADNP2 has been associated with developmental abnormalities, and CpG hypermethylation of ADNP2 has been linked with post-traumatic stress disorder (PTSD)." (PMID 39251453, 2024).
ADNP syndrome (1 paper, 2019). "The two predominantly opposite methylation signatures in ADNP syndrome (the ADNP-1 episignature is largely hypomethylated; the ADNP-2 episignature is hypermethylated) lead us to suspect that each mutation sub-group has unique cellular consequences." (PMID 31029150, 2019).
autism (1 paper, 2020). Persistent deficits in social interaction and communication and interaction as well as a markedly restricted repertoire of activity and interest as well as repetitive patterns of behavior. "While ADNP2 is a less studied gene compared to ADNP, recent studies have also linked ADNP2 deletion (together with other genes) to autism." (PMID 32937737, 2020).
metabolic syndrome (1 paper, 2025). A cluster of metabolic risk factors for CARDIOVASCULAR DISEASES and TYPE 2 DIABETES MELLITUS. "Of the 22 female-specific MDD/metabolic syndrome pleiotropic regions, possible causal risk loci mapped to multiple genes (GPC6, SHISA9, RP11-154H12.3, KCNG2, TXNL4A, RBFA and ADNP2)." (PMID 40858613, 2025).
cancer (2 papers, 2021 to 2024). A tumor composed of atypical neoplastic, often pleomorphic cells that invade other tissues. "Additionally, ADNP2, PCDH11X, and MGST1 detected to be highly expressed in the transformed HGG model have been associated with EMT and treatment resistance in various cancer types." (PMID 39256867, 2024). "related to proliferation and apoptosis of cancer cells and detected the changes of downstream target expression in CCA cells after further knockdown of AGAP2-AS1,including CDKN1A,ADNP2,SLC29A2 by qRT-PCR." (PMID 33522895, 2021).
ADNP2 also shares sentences with these, for which no sentence is quoted: Alzheimer disease (3 papers); Anxiety (1); autism spectrum disorder (1); brain disorder (1); cardiovascular disease (1); neuroblastoma (1).